SAMD9L (sterile alpha motif domain containing 9 like)
Description:
May be involved in endosome fusion. Mediates down-regulation of growth factor signaling via internalization of growth factor receptors.
Synonyms: C7orf6; DRIF2; KIAA2005; FLJ39885; ATXPC; C7DELq; DEL7q; M7MLS1; MLSM7; SCA49; UEF1
Tractability: PROTAC: ubiquitination databases record sites on it; its protein half-life has been measured.
Gene: Protein-coding gene on chromosome 7 (93,130,056 to 93,148,385, reverse strand). Ensembl gene ENSG00000177409.
Subcellular location: Early endosome; Mitochondrion
Subcellular location (Human Protein Atlas): Cytosol
Gene Ontology:
Molecular function: protein binding
Cellular component: mitochondrion; cytoplasm; early endosome
Genetic constraint (gnomAD): Loss-of-function variants: 68 observed, 95.02 expected, observed/expected ratio (o/e) 0.72, 90% interval 0.59 to 0.88. The upper end of that interval is the gene's LOEUF score, 0.88, which puts it in group 3 of 6, group 1 being the genes least tolerant of losing a copy. Missense variants: 1,598 observed, 1,918 expected, observed/expected ratio (o/e) 0.83, 90% interval 0.8 to 0.87. Synonymous variants: 638 observed, 665.46 expected, observed/expected ratio (o/e) 0.96, 90% interval 0.9 to 1.02.
Homologues: Orthologues: macaque SAMD9L (95% identical), rabbit SAMD9L (84% identical), dog SAMD9L (80% identical), guinea pig SAMD9L (76% identical), mouse Samd9l (72% identical), rat Samd9l (72% identical), zebrafish SAMD9 (38% identical), tropical clawed frog samd9l (34% identical). Paralogues in human: SAMD9 (60% identical).
Diseases named in the same sentence as SAMD9L in open-access papers:
SAMD9L is named in the same sentence as 70 diseases in open-access papers, as found by Europe PMC text mining. Sharing a sentence is not in itself a finding about the gene and the disease. The quoted sentences say what the papers report.
ataxia-pancytopenia syndrome (13 papers, 2017 to 2025). A rare genetic disease characterized by cerebellar ataxia, cytopenias and predisposition to bone marrow failure and myeloid leukemia. "SCA49 is caused by a missense mutation in the SAMD9L gene whose heterologous gain-of-function alleles have been described previously in causing the Ataxia-pancytopenia syndrome." (PMID 39725709, 2024). "Ataxia- pancytopenia syndrome (ATXPC) due to heterozygous variants in SAMD9L was first reported in 2016." (PMID 39083076, 2024). "In addition, she was found to have a new germline variant mutation in the SAMD9L gene (other known pathogenic variants known to cause ataxia pancytopenia syndrome)." (PMID 36880537, 2023). "Variants in SAMD9L have been reported to cause ataxia-pancytopenia syndrome (AP) (OMIM # 159550)." (PMID 33710394, 2021). "Missense mutations in SAMD9L gene is associated with ataxia-pancytopenia syndrome (ATXPC), OMIM#159550." (PMID 31053103, 2019). "Mutations in the SAMD9L gene, located in chromosome 7, are primarily associated with the ataxia-pancytopenia syndrome (ATXPC), myeloplasia and leukemia syndrome with monosomy 7 (MLSM7)." (PMID 31053103, 2019). "Case 4: Crypto 4 was a 12-year-old child affected by sterile alpha motif domain containing 9 like (SAM9DL) primary immunodeficiency (SAMD9L–Ataxia–Pancytopenia Syndrome, SAPS)." (PMID 40005709, 2025). "Very recently, heterozygous mutations causing a putative gain of function of the growth-suppressing effects of SAMD9L have been reported in human ataxia-pancytopenia syndrome." (PMID 28346228, 2017). "Germline mutations in the SAMD9 and SAMD9L genes, located in tandem on chromosome 7, are associated with a clinical spectrum of disorders including the MIRAGE syndrome, ataxia–pancytopenia syndrome and myelodysplasia and leukemia syndrome with monosomy 7 syndrome." (PMID 29535429, 2018). "Similar mutations in SAMD9 and SAMD9L have previously been observed in disorders associated with BM abnormalities, such as MIRAGE syndrome and Ataxia-Pancytopenia syndrome (ATXPC), respectively." (PMID 33731850, 2021).
myelodysplastic syndrome (13 papers, 2013 to 2025). A clonal hematopoietic disorder characterized by dysplasia and ineffective hematopoiesis in one or more of the hematopoietic cell lines. "SAMD9L mutations have been implicated in other cancers as contributors to tumor survival under stress, such as in gastric cancer and myelodysplastic syndrome; however, their role in LSCC metastasis is largely unexplored." (PMID 41590495, 2025). "In the pediatric age group, germline abnormalities in GATA2, SAMD9, and SAMD9L are the most common causes of myelodysplastic neoplasms and AML." (PMID 39062641, 2024). "While UPD7q and loss-of-function somatic SAMD9L variants may restore hematopoiesis, monosomy 7 or deletion of 7q can lead to the development of myelodysplastic syndrome." (PMID 36553623, 2022). "Germline mutations in sterile alpha motif domain protein 9 (SAMD9) and its paralogue SAMD9-like (SAMD9L), which are located in tandem on chromosome 7q21, are associated with human syndrome with a propensity for bone marrow failure and myelodysplastic syndrome (MDS) with monosomy 7 and 7q deletion." (PMID 34868061, 2021). "However, when monosomy 7 occurs there is a risk of myelodysplastic syndrome due to loss of SAMD9, SAMD9L, GATA2 and other factors, and an additional risk of leukemia if further somatic changes occur." (PMID 36060959, 2022). "Germline mutations in the SAMD9 and SAMD9L gene, located on chromosome 7, are associated with a clinical spectrum of disorders including the MIRAGE syndrome, ataxia–pancytopenia syndrome and monosomy 7 myelodysplastic syndrome." (PMID 35572556, 2022). "Similarly, loss of SAMD9 and SAMD9L by monosomy 7 or monosomy 7q (–7/7q–) is well established in myeloid lineage malignancies, and disruption of SAMD9L has been shown to be associated with the development of myelodysplastic syndrome (MDS) in mice and humans." (PMID 28346228, 2017). "Lastly, the human SAMD9 and SAMD9L genes were both classified as myeloid tumor suppressors, as they are localized within a microdeletion cluster associated with myeloid disorders, such as juvenile myelomonocytic leukemia (JMML), acute myeloid leukemia (AML), and myelodysplastic syndrome (MDS)." (PMID 23758988, 2013). "In conjunction with IBMF, MIRAGE syndrome patients show an increased risk of myelodysplastic syndrome (MDS) associated with microdeletions in chromosome 7 (monosomy 7), indeed 17% of pediatric patients with MDS have mutations in SAMD9 and its paralogue SAMD9L." (PMID 41268294, 2025).
viral infection (9 papers, 2013 to 2024). "SAMD9L is a myeloid tumour suppressor gene, which has been shown to involved in the innate response to viral infection and also plays a role in regulating the response to type I interferons in haematopoietic cells and other cell types e.g. T-cells." (PMID 35720382, 2022). "SAMD9L is a type I interferon‐induced gene that has important roles during virus infection and innate immunity." (PMID 35388602, 2022). "OASL and SAMD9L have been shown to be important in viral infection and innate immunity, but the mechanism of their action is different from that of ISG15." (PMID 34920753, 2021). "Samd9l is a Sam domain containing protein which has important roles during virus infection and innate immunity." (PMID 31665046, 2019). "Samd9l is a Sam domain containing protein with similarities to SAMD9 which has been shown to be important during virus infection and innate immunity." (PMID 25418976, 2014). "SAMD9 and SAMD9L have also recently been shown to play key roles in the innate immune responses to stimuli such as viral infection." (PMID 23758988, 2013). "This suggests that SAMD9L virus-specific effect may involve a differential SAMD9L activation—dependent on its capacity to sense a given viral infection—and on the virus ability to escape from SAMD9L restriction." (PMID 38959200, 2024). "An alternative hypothesis is that Samd9l affects the persistence of ligand-bound cytokine receptors which may increase cytokine signaling and inflammation which in turn results in more recruitment of inflammatory cells and virus infection." (PMID 25418976, 2014). "Part of this genetic locus, including Samd9l, was also reported to modulate proinflammatory cytokines, including TNF-α and IFN-α, after viral infections." (PMID 36074606, 2022). "In particular, 8 genes (Mx1, EPSTI1, XAF1, IFI44L, GBP1, SAMD9, SAMD9L, and CMPK2) were expressed in the highly resistant cell lines HPAF-II and Hs766T but not the highly permissive cell lines MIA PaCa-2 and Capan-1 in the absence of virus infection." (PMID 27533247, 2016).
Ataxia (7 papers, 2018 to 2024). Ataxia refers to impaired coordination of voluntary muscle movement. "The functional studies in patients’ fibroblasts demonstrated for the first time the mitochondrial localization of human SAMD9L protein and mitochondrial perturbations underlying the molecular pathology in this new ataxia subtype." (PMID 35310830, 2022). "A novel SCA49 spinocerebellar ataxia subtype has been described, caused by SAMD9L mutation, which triggers mitochondrial alterations, pointing to a role of SAMD9L in neurological motor and sensory functions." (PMID 36005139, 2022). "Likewise, the analysis of human ENCODE RNA data corroborated the expression of SAMD9L predominantly in Purkinje cells, cerebellum and spinal cord, which are the main tissues affected in this new ataxia subtype." (PMID 35310830, 2022). "This study describes a novel spinocerebellar ataxia subtype caused by SAMD9L mutation, SCA49, which triggers mitochondrial alterations pointing to a role of SAMD9L in neurological motor and sensory functions." (PMID 35310830, 2022). "Single patients were found to harbour mutations in ATM, SAMD9L, or FMRI that have occasionally been reported as a cause of inherited ataxia." (PMID 34600502, 2021). "RNA tissue expression also showed higher levels of SAMD9L in child cerebellum and in embryonic cerebellum and spinal cord, in consonance with stages of high mitochondrial activity and tissues affected in the pathogenesis of this new ataxia subtype." (PMID 35310830, 2022). "Based on his prominent ataxia and family history of monosomy 7‐MDS, genetic testing was performed, which revealed a missense VUS in SAMD9L, present only in 16% of sequencing‐reads, suggestive of mosaicism." (PMID 38594844, 2024).
Myelodysplasia (7 papers, 2018 to 2023). Clonal hematopoietic stem cell disorders characterized by dysplasia (ineffective production) in one or more hematopoietic cell lineages, leading to anemia and cytopenia. "Although the loss of Samd9l in mice results in a myelodysplasia-like phenotype, the function of SAMD9 and SAMD9L, and the impact of pathogenic germline mutations, in hematopoietic cells has yet to be determined." (PMID 33731850, 2021). "GoF SAMD9 mutations cause MIRAGE (myelodysplasia, infection, restriction of growth, adrenal hypoplasia, genital phenotypes, and enteropathy) disorder, while GoF SAMD9L mutations cause a similar disorder characterized with cytopenia, immunodeficiency, and neurological symptoms." (PMID 29447249, 2018). "SAM domain-containing proteins are implicated in normal and pathologic mechanisms, including SAMHD1 in autoimmunity and SAMD9/SAMD9L in myelodysplasia and myeloid malignancies." (PMID 32241909, 2020).
COVID-19 (6 papers, 2021 to 2025). A disease caused by infection with severe acute respiratory syndrome coronavirus 2. "The identification of SAMD9L as a downregulated gene in severe COVID-19 highlights its potential role as a critical host restriction factor that SARS-CoV-2 must overcome to establish infection." (PMID 41168347, 2025). "The suppression of SAMD9L in individuals with severe COVID-19 suggests that it may also be a critical host restriction factor that SARS-CoV-2 must antagonize to establish disease." (PMID 38375062, 2024). "The SAMD9L pathway was previously shown to be a critical host barrier that poxviruses subvert most to establish an infection and was among the ISGs found to be significantly downregulated in Ghanaians with severe COVID-19 compared with mild cases." (PMID 38375062, 2024). "Moreover, in people with severe COVID-19 the infection reveals a diminished antiviral response marked by the downregulation of antiviral genes such as OAS1, SAMD9L and IFIT2, and suppression of antiviral immune response pathways." (PMID 41168347, 2025).
myeloid malignancies (6 papers, 2018 to 2024). "Germline G-o-F mutations in SAMD9L are responsible for diverse multisystem disorders, including myeloid malignancies and systemic autoinflammatory diseases in humans." (PMID 38959200, 2024). "SAMD9 and SAMD9L germline mutations have recently emerged as a new class of predispositions to pediatric myeloid neoplasms." (PMID 36074606, 2022). "In addition to the germline mutations observed in patients with BMF and myeloid neoplasms, SAMD9L mutations have been associated with inflammatory diseases." (PMID 36074606, 2022). "In addition, SAM domain proteins can be implicated in human pathogenic mechanisms, e.g. SAMD9 and SAMD9L mutations are linked to bone marrow failure that can progress to myeloid malignancies." (PMID 32241909, 2020). "In mice, SAMD9L haploinsufficiency caused myeloid malignancies." (PMID 29447249, 2018). "Mouse SAMD9L is also a tumor suppressor, and haploinsufficiency of mouse SAMD9L resulted in myeloid malignancies." (PMID 29447249, 2018).
Pancytopenia (6 papers, 2018 to 2026). An abnormal reduction in numbers of all blood cell types (red blood cells, white blood cells, and platelets). "We report a 6-month-old girl presenting with pancytopenia and severe infections, in whom we identified a novel heterozygous SAMD9L variant." (PMID 42154215, 2026). "Our in vivo model recapitulates many of the clinical manifestations of patients with SAMD9L mutations, including pancytopenia, BM hypocellularity, and incomplete clinical penetrance." (PMID 36074606, 2022). "Pathogenic SAMD9L variants represent gain-of-function variants and have an adverse effect on cell proliferation which in turn causes pancytopenia and pressure to eliminate the mutant SAMD9L allele." (PMID 36553623, 2022). "Germline gain-of-function (GOF) mutations, therefore, increase SAMD9 or SAMD9L antiproliferative effect causing pancytopenia, BMF and generally restricted growth and/or specific organ hypoplasia in non-hematopoietic tissues in an autosomal dominant fashion." (PMID 33802366, 2021). "Together, our data demonstrated that inflammation potentiates Samd9l-Mut phenotypes, in particular, pancytopenia with lymphopenia, corresponding to clinical observations in patients with SAMD9L mutations." (PMID 36074606, 2022). "In support of these data, RBCs and platelets were significantly reduced exclusively in the pI:pC-treated Samd9l-Mut mice, consistent with pancytopenia." (PMID 36074606, 2022). "Gain-of-function mutations in SAMD9 and SAMD9L, located on chromosome 7, enhance antiproliferative effects, leading to pancytopenia and restricted growth or organ hypoplasia in non-hematopoietic tissues." (PMID 40358701, 2025).
MIRAGE syndrome (4 papers, 2018 to 2024). An autosomal dominant condition caused by mutation(s) in the SAMD9 gene, encoding sterile alpha motif domain-containing protein 9A. "The authors showed that complex dynamic somatic changes in SAMD9 and the SAMD9/SAMD9L locus on chromosome 7q are associated with the distinct MIRAGE syndrome phenotype and modify survival in affected patients." (PMID 38539345, 2024). "Similar to the observations made for GOF SAMD9L mutations in ATXPC, GOF SAMD9 mutations were also reverted by other genetic mechanisms such as frame-shift or stop gain mutations in the blood of four individuals with MIRAGE syndrome, including patients with non-manifest hematopoietic phenotype." (PMID 29535429, 2018).
bone marrow failure syndrome (3 papers, 2017 to 2024). "MDS with monosomy 7 frequently occurs in patients with germline variants in GATA-binding factor 2 (GATA2), sterile alpha motif domain containing 9 (SAMD9), sterile alpha motif domain containing 9 like (SAMD9L), or hereditary bone marrow failure syndrome." (PMID 38203823, 2024).
Immunodeficiency (3 papers, 2018 to 2026). Failure of the immune system to protect the body adequately from infection, due to the absence or insufficiency of some component process or substance. "Germline gain-of-function variants in sterile alpha motif domain-containing 9-like (SAMD9L), located on chromosome 7q, cause a multisystem disorder characterized by bone marrow failure, immunodeficiency and variable neurological involvement." (PMID 42154215, 2026). "SAMD9L activity has been shown in immunodeficiency, MDS and neurological symptoms." (PMID 30086151, 2018).
Ataxia - pancytopenia (2 papers, 2022 to 2025). "Interestingly, MIRAGE phenotypic features have also recently been described in two patients carrying SAMD9L variants, which are associated with MDS and in some cases Ataxia pancytopenia (OMIM:159550) and CANDLE phenotypes." (PMID 36060959, 2022).
autoimmune disease (2 papers, 2024 to 2025). A disorder resulting from loss of function or tissue destruction of an organ or multiple organs, arising from humoral or cellular immune responses of the individual to their own tissue constituents. "Examples of autosomal genes with a female bias in macrophages include Fcgr2b, Samd9l, and Ccr5, which have been implicated in autoimmune diseases." (PMID 38496477, 2024).
breast carcinoma (2 papers, 2007 to 2021). "Using the sequences at 3'UTR of SAMD9L as primers, SAMD9L was also found to be expressed in all tissues, except for the tumor types, colon cancer (CX-1), breast cancer (GI-101) and pancreatic cancer (GI-103)." (PMID 17407603, 2007). "SAMD9 is expressed at a lower level in aggressive fibromatosis and some cases of breast and colon cancer, while SAMD9L is expressed at a lower level in breast cancer, compared to normal control tissues from the same patients." (PMID 17407603, 2007). "However, the expression of SAMD9L was lower in breast cancers than in healthy breast epithelial tissues from the same patients (2.81% ± 2.40% vs 100%, n = 10, p < 0.001)." (PMID 17407603, 2007). "Similarly, low expression of SAMD9L, positively correlated with CD274, was beneficial for lymphoma patients, whereas high expression of the same gene was beneficial for melanoma and breast cancer patients." (PMID 34067485, 2021).
Cerebellar atrophy (2 papers, 2025). Cerebellar atrophy is defined as a cerebellum with initially normal structures, in a posterior fossa with normal size, which displays enlarged fissures (interfolial spaces) in comparison to the foliae secondary to loss of tissue. "Progressive cerebellar atrophy was associated with progressive ataxia only in four cases (40%; ATM, CACNA1A, FXN, and SAMD9L)." (PMID 40326640, 2025). "Of note, three patients were found to have pathogenic variants in the ATM and SAMD9L genes but did not display evidence of cerebellar atrophy at the time of available brain MRI scans." (PMID 40326640, 2025).
colon cancer (2 papers, 2007 to 2017). "SAMD9 and SAMD9L are significantly down-regulated in various neoplasms including aggressive fibromatosis, breast and colon cancers." (PMID 28545555, 2017).